RPS3 (ribosomal protein S3)
Diseases named in the same sentence as RPS3 in open-access papers (continued):
Sharing a sentence is not in itself a finding about the gene and the disease.
tumor (continued). "A study showed that, in gastric cell lines, exosomal Ribosomal Protein S3 (RPS3) secreted by cisplatin-resistant tumor cells could be taken up by cisplatin-sensitive cells and thus become chemoresistant (through activation of the PI3K-Akt-cofilin-1 signaling pathway)." (PMID 34068319, 2021). "Exosomal Ribosomal Protein S3 (RPS3) secreted by cisplatin-resistant tumor cells could be taken up by cisplatin-sensitive cells and thus become chemo resistant (through activation of the PI3K-Akt-cofilin-1 signaling pathway), indicating its potential value for proper chemotherapeutics selection." (PMID 34307129, 2021). "In accordance with the results of mass spectrometric profiling of tumor tissue proteomes obtained from the control and treated groups of animals, the results of Western blot analysis have also revealed decreased levels of Rps3 in all treated groups in comparison with the control group." (PMID 32973493, 2020). "Furthermore, RPS3 is confirmed to be safe when using as an adjuvant in tumor-specific antigen DC-based vaccines via TLR4 since RPS3 is nucleoprotein that could induce humoral immunity, producing autoantibodies against itself." (PMID 30819254, 2019). "Furthermore, RPS3 was released from not only B16F1 and B16F10 tumor cells but also normal cells like BMDCs when they were treated with doxorubicin and the released RPS3 could bind to TLR4." (PMID 30819254, 2019). "In addition, rpS3 is involved in the invasion of tumor cells." (PMID 27384988, 2016). "It does so by encoding the protein circPLCE1-411, which in turn reduces the expression level of RPS3 within CRC cells, thereby exerting its tumor-suppressive effect." (PMID 41169378, 2025). "In cancerous cells, the ubiquitination of specific RPs can promote tumour invasion, tumour metastasis, and resistance to chemotherapy treatment, thereby contributing to tumour progression (see sections on RPL5, RPL11, RPS3, and RPL23a)." (PMID 40940922, 2025). "Mass spectrometric analysis of tumours revealed that STAT1 (signal transducer and activator of transcription 1) is bound to RPS3." (PMID 40940922, 2025). "After analysis of a series of bioinformatics data of tumor-derived Igλ, we obtained four potential tumor-derived Igλ-interacting proteins, namely RPL7, RPS3, H1-5, and H1-6, using Co-IP combined with LC–MS/MS." (PMID 37784026, 2023). "Compared with the SIAH1 + FLAG-RPS3 group, transfection with SIAH1 + FLAG-RPS3(K214R) resulted in a larger tumour volume, more tumours, higher RPS3 protein expression, lower apoptosis rates and higher proliferation rates." (PMID 35951361, 2022). "In NSCLC, ionizing radiation (IR) induces dissociation of the MIF-ribosomal protein S3 (rpS3) complex and enhances MIF expression, which activates the NF-kB signal and triggers EMT of tumor cells." (PMID 35842634, 2022). "Recombinant RPS3 induced maturation and activation of DCs, and following pulsing with tumor specific antigens, these DCs could be used as a vaccine to significantly increase tumor specific CD8+IFN-γ+ T cells, and provide both tumor prevention and tumor treatment effects." (PMID 30819254, 2019). "As a result, the survival of mice vaccinated with RPS3-activated DCs decreased when the mice were also injected with a CD8-depleting antibody, indicating that CD8+ T cells function to prevent tumor formation and have an antitumor effect." (PMID 30819254, 2019). "In our previous studies, not only RPS3, but also several ribosomal proteins that bind to TLR4 were screened from human tumor cells." (PMID 30819254, 2019). "It is thought that knockdown of RPS3 reduces the invasive ability of ACC, and on the other hand, it may inhibit tumor growth and reduce nerve compression." (PMID 35847905, 2022).
tumor (continued). "RPS3 induces maturation and activation of dendritic cells, acting as a new ligand for TLR4 in the innate immune system, and significantly increases CD8+ T cell production in the presence of a tumor-specific antigen in the adaptive immune system." (PMID 30819254, 2019). "SKOV3 supernatant does not seem to release RPS3 due to merely effects of doxorubicin occurring cell death in SKOV3 compared to other tumor cells." (PMID 30819254, 2019). "The tumor treatment effect was absent in mice injected with the RPS3-treated DCs lacking TLR4 and pulsed with E7." (PMID 30819254, 2019). "The number of tumor specific CD8+IFN-γ+ T cells was greatly increased when mice were vaccinated with RPS3-activated wild type DCs pulsed with E7, but not with RSP3 treated TLR4−/− DCs pulsed with E7." (PMID 30819254, 2019). "In addition, RPL7 directly interacts with RPS3, while H1-5 or H1-6 has no direct interaction with other three tumor-derived Igλ-interacting proteins respectively." (PMID 37784026, 2023). "Also well-known is the involvement of RP uS3 (RPS3) and uS2 (RPSA) in the invasion and metastasis of tumor cells (note that uS2 (RPSA) may work outside the ribosome as a laminin receptor)." (PMID 37511213, 2023). "There was a notable divergence in gene expression levels between neoplastic and neighboring tissues, with genes such as BRCA1, CHEK2, and IKBKE substantially amplified in tumor tissues, while genes such as ZMYND11, MAPK8, and RPS3 exhibited notable elevation in adjacent nontumor tissues." (PMID 41497799, 2025).
bacterial infection (3 papers, 2018 to 2025). "RPS3 leads kappa light chain enhancer of NF-κB subunit of activated B cells to specific κB site, which plays an important role in the innate response of bacterial infection." (PMID 32609751, 2020). "The ribosomal protein S3 (RPS3) guides NF-κB subunits to specific κB sites and plays an important role in the innate response to bacterial infection." (PMID 30405005, 2018).
neurological diseases (1 paper, 2018). "Further studies are necessary to determine whether CHIP-mediated RPS3 degradation helps to prevent neuronal death in starvation and whether manipulation of RPS3 stability by CHIP provides novel insights for the development of novel therapeutics for neurological diseases." (PMID 30213050, 2018).
RPS3 also shares sentences with these, for which no sentence is quoted: HCMV infection (3 papers); Herpesvirus infection (3); latent infection (3); epithelial ovarian cancer (2); acute kidney injury (1); adenoma (1); blepharitis (1); bubonic plague (1); chronic myeloid leukemia (1); clear cell renal cell carcinoma (1); dementia (1); diabetic foot ulcers (1); esophageal cancer (1); HIV-1 infection (1); lung carcinoma (1); metastatic disease (1); neuroblastoma (1); ocular infection (1); oral cancer (1); ovarian cancer (1); prostate carcinoma (1); reproductive diseases (1); sarcoma (1); Schopf-Schulz-Passarge Syndrome (1); Sepsis (1); teratozoospermia (1).